PIN1 (peptidylprolyl cis/trans isomerase, NIMA-interacting 1)
Diseases named in the same sentence as PIN1 in open-access papers (continued):
Sharing a sentence is not in itself a finding about the gene and the disease.
cancer (continued). "As a major common regulator of numerous cancer-driving pathways and a unique therapeutic target, the prolyl isomerase Pin1 is overexpressed in a majority of HCCs, whereas the mechanism underlying Pin1 overexpression remains elusive." (PMID 28383568, 2017). "Mechanistically, both genetic and chemical inhibition of Pin1 downregulates multiple cancer-driving pathways." (PMID 28262728, 2017). "All tested cancer cells expressed higher levels of PIN1 and were more sensitive to KPT-6566, even at low micromolar concentrations." (PMID 28598431, 2017). "Through the regulation of diverse oncogenic signaling pathways including growth-signal responses, cell-cycle progression, cellular stress responses, neuronal function and immune responses, PIN1 plays an important role during cancer development." (PMID 28676695, 2017). "PIN1 is over-expressed in cancers of many organs, including breast, lung, and prostate, and is involved in carcinogenesis." (PMID 28076852, 2017). "The prolyl isomerase PIN1, a critical modifier of multiple signalling pathways, is overexpressed in the majority of cancers and its activity strongly contributes to tumour initiation and progression." (PMID 28598431, 2017). "The unique prolyl isomerase, Pin1 is prevalently overexpressed or over-activated in many types of cancer including HCC." (PMID 28404959, 2017). "Here, we show that either chemical or genetic Pin1 inhibition potently suppresses HCC growth by blocking multiple cancer-driving pathways." (PMID 28262728, 2017). "Clinical studies have shown that Pin1 is frequently overexpressed in different cancers and in some cases its overexpression correlates with clinical outcome." (PMID 28426725, 2017). "High Pin1 expression has been shown to be an independent factor for cancer development and poor prognosis and is along with larger tumor size and increased portal vein invasion of HCC48." (PMID 28383568, 2017). "Inactivation of PIN1 function conversely curbs tumour growth and cancer stem cell expansion, restores chemosensitivity and blocks metastatic spread, thus providing the rationale for a therapeutic strategy based on PIN1 inhibition." (PMID 28598431, 2017). "More importantly, a similar inhibition of multiple Pin1 downstream cancer-driving pathways was also found after chemical inhibition of Pin1 by its inhibitor ATRA." (PMID 28262728, 2017). "The present study uncovers for the first time that miR-140-5p directly targets Pin1 to block multiple cancer-driving pathways and exert potent antitumor activity in vitro and in vivo." (PMID 28383568, 2017). "Pin1 overexpression promotes tumorigenesis by activating multiple cancer-driving pathways at the same time." (PMID 28383568, 2017). "Although the clinical relevance of Pin1 and Grb7 expression during oncogenesis remains to be examined, both molecules have been known to be often involved in cancer progression." (PMID 27658202, 2016). "Thus, while it may appear as if Pin1 deficiency exerts opposite effects on two representative age-related diseases, this is actually due to the differences in the features of neuronal versus cancer cells." (PMID 27618008, 2016). "Further studies are required to fully elucidate the role of PIN1 in regulating these cancer-related signaling pathways in NPC." (PMID 27258148, 2016). "Pin1 is vigorously overexpressed in diverse of human cancers, such as breast and prostate cancer, required for activity and cross-talk of oncogenic pathways." (PMID 27029791, 2016). "A recent study provided new insights into the opposite role of PIN1 in the pathogenesis of cancer and AD." (PMID 26784107, 2016). "In various malignancies, Pin1 expression levels are increased, and Pin1 gene silencing or knockdown suppresses cancer cell proliferation and migration." (PMID 27618008, 2016). "Pin1 is upregulated in several cancers and has also been targeted for anti-cancer therapy by several laboratories." (PMID 25992900, 2015).
cancer (continued). "IPA software was used to categorize the cancer related genes of which expressions were significantly changed (≧1.5-FC) by Pin1 knockdown in the IPA database." (PMID 26039047, 2015). "In Ad-ZBP-89-infected Pin1+/+ cancer cells, Pin1 siRNA increased HDAC3 but decreased Bak, compared with cells without ZBP-89 infection." (PMID 25623232, 2015). "Dysregulation of Pin1 is implicated in human cancers, and KSHV is the latest virus known to co-opt Pin1 function." (PMID 25588053, 2015). "The protein interacting with NIMA 1 (Pin1) gene, which is overexpressed in some types of human cancers, is up- or down-regulated in AD brains (depending on brain region)." (PMID 25394409, 2014). "In fact, several drugs designed to inhibit Pin1 are currently in clinical trial for treating cancers." (PMID 25398907, 2014). "Taken together, this study provides the rationale for the development of specific Pin1 inhibitors as potential anti-cancer agents." (PMID 24899581, 2014). "By contrast, ablation of Pin1 prevents cancer but eventually leads to premature ageing and neurodegeneration." (PMID 24877062, 2014). "Consistently, depletion of Pin1 caused higher expression of FBW7, subsequently decreased Mcl-1 abundance, leading to enhanced Taxol sensitivity in cancer cells." (PMID 24899581, 2014). "In particular, Pin1 is required for full activity and cross-talk of a variety of oncogenic pathways in breast and other cancers, acting as an amplifier of phosphorylation signals." (PMID 24357640, 2014). "Pin1 is overexpressed in most human cancers; it activates numerous oncogenes or growth enhancers and also inactivates a large number of tumour suppressors or growth inhibitors." (PMID 24877062, 2014). "Drug companies such as Pfizer Global R&D and Vernalis Ltd as well as several academic laboratories have targeted Pin1 for anti-cancer therapy." (PMID 24416409, 2014). "In their article, they highlight the interactions of Pin1 with key proteins relevant to cancer and cancer therapy and discuss how Pin1 specifies cell fate decision in response to DNA damage." (PMID 25401089, 2014). "Pin1 is a peptidyl-prolyl isomerase, which has been shown to be highly expressed in several cancers including prostate, breast, lung and colon cancers." (PMID 25398907, 2014). "Of note, since Pin1 overexpression is frequently observed in cancer, this mechanism is presumably involved in the increased genomic instability observed in human cancer cells." (PMID 24982848, 2014). "These targets of PIN1 play a key role in the regulation of the cell cycle and are often deregulated in cancer." (PMID 24179535, 2013). "The results revealed that the migration and invasion abilities of the cancer cells were significantly reduced with the RNAi-mediated knockdown of PIN1 expression in the RBE cells." (PMID 24179535, 2013). "The possible involvement of PIN1 in human carcinogenesis is based on the observations that the overexpression of the gene is frequently identified in human cancers." (PMID 24179535, 2013). "It has been reported that PIN1 is aberrantly over-expressed in some common cancers, such as lung, breast, colon and prostate cancers." (PMID 23874525, 2013). "The increased expression of Pin1 in inflammation and in cancer is therefore predicted to selectively enhance GR transactivation, with consequences for cell function in that environment." (PMID 23887939, 2013). "Growing evidence has shown that Pin1 is involved in the pathogenesis of certain cancers and protein folding illnesses like Alzheimer's and Parkinson's disease." (PMID 23750710, 2013).
cancer (continued). "Although ERK2 and Pin1 are frequently elevated in many cancers, the link to reduced PML levels in vivo is yet to be demonstrated." (PMID 23730625, 2013). "As Pin1 has been shown to modulate several NHRs and is regulated in both inflammation and cancer, we investigated its role in glucocorticoid action." (PMID 23887939, 2013). "Pin1 plays critical roles in various types of cancer by changing target protein stability through a ubiquitin-mediated mechanism." (PMID 23708493, 2013). "Peptidyl-prolyl cis–trans isomerase NIMA-interacting 1 (PIN1) plays an important role in cancer development." (PMID 24013949, 2013). "Pin1 is involved not only in the pathogenesis of human cancer, but - presumably - also in the pathogenesis of asthma and Alzheimer's disease." (PMID 21219594, 2011). "In most cancers we found nuclear and cytoplasmic localization of Pin1; however, in some cancers we saw only nuclear staining." (PMID 19077306, 2008). "Of the Her2-positive cancers 40 (62.5%) were also Pin1-positive, based on strong nuclear or nuclear and cytoplasmic staining." (PMID 19077306, 2008). "Consistent with such a function, overexpression of Pin1 has been observed in many cancers, and its levels are predictive of cancer recurrence." (PMID 17311089, 2007). "Pin1 facilitates the cancer progression through regulating different substrates at several levels." (PMID 41246306, 2025). "The development of such new-generation small molecule PIN1 inhibitors that mitigate the effects of PIN1 overexpression in cancer cells could reignite PIN1 drug development efforts." (PMID 40087364, 2025). "The peptidyl-prolyl isomerase protein Pin1 has been shown to contribute to cancer onset, development, and progression by regulating the function and stability of oncogenes and tumor suppressors, both in cancer cells and surrounding stromal cells." (PMID 41322199, 2025). "In addition, genetically engineered mice lacking Pin1 are highly resistant to tumorigenesis and are phenotypically normal, while in humans, genetic alterations that result in diminished Pin1 expression correlate with a reduced incidence of cancer." (PMID 41322199, 2025). "Pin1's role as a regulator of protein function through isomerization of phosphorylated serine/threonine-proline motifs has been previously documented in various contexts, including cancer and neurodegenerative diseases." (PMID 41477119, 2025). "reviewed that targeting Pin1 as a promising strategy to overcome resistance to cancer therapies." (PMID 41246306, 2025). "Thus, enormous efforts have been put into the study concerning the regulation of Pin1 expression, leading to the discovery of multiple layers of mechanisms controlling Pin1 levels in cancers." (PMID 38167292, 2024). "Finally, Pin1 is highly expressed in cancer stem cells and supports the self-renewal of these poorly differentiated tumor cells, but the detailed downstream effectors remain elusive." (PMID 38167292, 2024). "Moreover, epigallocatechin 3 gallate (EGCG), a component of green tea, functions as a cancer chemo-preventive agent that can be applied to inhibit Pin1." (PMID 39624096, 2024). "Thus, Pin1 indirectly promotes cancer development by eliminating the Fbw7 inhibition of oncogenic activities, such as the self-renewal of cancer stem cells through Notch signaling." (PMID 38727267, 2024).
cancer (continued). "Given that Pin1 plays an essential role in the maintenance of a cancer stem-cell phenotype, combination therapies that include a Pin1 inhibitor are an attractive approach to sensitizing drug-resistant CSCs to treatment with cytotoxic agents that were not effective in the absence of Pin1 inhibition." (PMID 38745861, 2024). "Future studies may discover more inhibitors for CDK1 and Pin1 to achieve the combination therapy for cancer treatment." (PMID 38167292, 2024). "Additionally, rhein exerts antitumor effects by interfering with the Pin1/c-Jun interaction, thus contributing to strategies for cancer prevention or therapy." (PMID 39624096, 2024). "Interrupting the Pin1/CDK1/pVHL axis results in decreased cancer cell proliferation, migration, invasion, and chemoresistance, and therefore it could be therapeutically valuable in treating cancers with wild-type VHL." (PMID 38727267, 2024). "Normal cells have lower Pin1 expression than cancer cells; therefore, the Pin1-dependent cytotoxic effects of KPT-6566 could be used to specifically target cancer cells." (PMID 38745861, 2024). "The inactivation of Pin1 protein function restores chemosensitivity, curtails the expansion of cancer stem cells and tumor growth, and may eventually block metastatic spread." (PMID 39624096, 2024). "Accordingly, Pin1 overexpression is correlated with poor clinical outcomes in numerous cancers." (PMID 38745861, 2024). "This review examines the complex role of Pin1 in the development and treatment of cancer." (PMID 38745861, 2024). "Consequently, the Pin1 levels in cancer are often correlated with poor clinical outcomes and act as a key prognostic marker in many cancer types." (PMID 38727267, 2024). "However, the same group later reported that Pin1 stabilizes Myc and enhances its DNA-binding propensity in cancer cells." (PMID 38745861, 2024). "These compounds hold great potential for further exploration regarding their efficacy and safety as Pin1 inhibitors, which could usher in new avenues for combating cancer." (PMID 38318109, 2024). "By modulating the CtlP stability, Pin1 contributes to the phosphorylation-dependent regulation of DNA double-stranded repair mechanisms, indicating that abnormal Pin1 levels, like in cancer, can compromise the efficacy of the HR and NHEJ repair mechanisms and, consequently, the genomic integrity." (PMID 38727267, 2024). "Another Pin1 phosphosite that can be altered in cancer is Ser138." (PMID 38745861, 2024). "Similarly, Pin1 depletion sensitized in vitro cancer cells to Taxol by upregulating Fwb7 and subsequently decreasing the levels of the oncogene Mcl-1." (PMID 38727267, 2024). "The peptidyl-prolyl cis-trans isomerase Pin1 is a pivotal therapeutic target in cancers, but the regulation of Pin1 protein stability is largely unknown." (PMID 38167292, 2024). "PIN1 induces cancer metastasis and invasion by activating β-catenin, BRD4, NF-κB, and p53M." (PMID 39202474, 2024). "However, the efficacy of using Pin1 as a target in cancer therapy is highly dependent on the cellular context." (PMID 39624096, 2024). "Furthermore, PIN1 promotes the generation of fatty acids which are used as energy fuel, membrane synthesis, and cell signaling in rapidly proliferating cancer cells." (PMID 38786739, 2024). "PIN1 is considered a potential target for tumours, and several PIN1 inhibitors and chemotherapeutics have been designed and developed to reduce cell proliferation, repress tumorigenesis or overcome resistance to cancer therapies." (PMID 37929660, 2024). "Considering that both Pin1-catalyzed isomerization and Ubc9-mediated sumoylation have several substrates, simultaneous targeting of Pin1 expression and Ubc9 isomerization may have outstanding anti-cancer effects in multiple cancers." (PMID 38167292, 2024).
cancer (continued). "Additionally, Pin1 enhances drug resistance and promotes changes in the tumor microenvironment that are conducive to cancer cell survival." (PMID 39624096, 2024). "Interestingly, while DMG samples showed significantly higher expression of MYC and its target genes compared to normal samples, PIN1 expression was lower in the cancer compared to matched normal tissue." (PMID 39093942, 2024). "However, the PPIase activity is essential for the functions of peptidyl-prolyl cis-trans isomerase NIMA-interacting 1 (Pin1), which promotes malignant development of several kinds of cancers." (PMID 38167292, 2024). "Pin1 is primarily elevated in cancer but downregulated in AD." (PMID 38534454, 2024). "Our work suggests that direct impairment of Pin1 protein stability may be an effective way to target Pin1 signaling in cancers." (PMID 38167292, 2024). "Pin1 is frequently overexpressed in various human cancers, such as prostate and lung cancers." (PMID 38534454, 2024). "These facts make Pin1 an attractive drug target for cancer treatment, and inducing Pin1 protein degradation may have strong therapeutic effects." (PMID 38167292, 2024). "Higher expression of PIN1 was found in cancer tissues with larger tumour sizes." (PMID 37929660, 2024). "This interaction subsequently inhibits intracellular Pin1 activity and the proliferation of different cancer cell lines, including HeLa and BT-474, whilst also elevating the levels of PML and SMRT (silencing mediator for retinoic acid and thyroid hormone receptors)." (PMID 39624096, 2024). "In summary, Pin1 is the crucial PPIase with a central role in signaling networks in cancers." (PMID 38167292, 2024). "However, recent studies suggest that Pin1 plays a prominent role in cancer-related immunosuppression." (PMID 38745861, 2024). "PIN1 is commonly upregulated in malignancies and contributes to the progression and development of tumours, suggesting that PIN1 represents a promising target for cancer." (PMID 37929660, 2024). "Pin1 signaling in cancer stem cells is a highly intricate and interconnected process." (PMID 38745861, 2024). "Both the APC/C and Rb are Pin1-regulated tumor suppressors that are largely inactivated in cancer." (PMID 38727267, 2024). "One study found that in 38 out of 60 human cancer types tested, Pin1 was overexpressed in 10% of these cases, suggesting that Pin1 overexpression is a critical event for tumorigenesis and may serve as an amplifier of oncogenic signaling." (PMID 38727267, 2024). "DAPK-1 may have the potential to enhance cancer treatment by inhibiting the oncogenic activity of Pin1." (PMID 39081443, 2024). "Therefore, targeting Pin1 activity presents an opportunity to attack cancer development through multiple downstream oncogenic targets simultaneously, curb the expansion of CSCs, and overcome immunosuppressive tumor environments." (PMID 38745861, 2024). "Despite previous reports showing that the knockdown of PIN1 leads to lower levels of cell proliferation and induction of senescence markers, with a vast majority of such studies being conducted in cancer cell models, our results show a protective role of PIN1 in the context of OIS." (PMID 38216124, 2024). "Indeed, with few exceptions, Pin1 promotes cancer progression and cancer stem cell expansion by increasing the stabilities of over 70 oncoproteins while decreasing the stabilities of over 35 tumor suppressors." (PMID 38727267, 2024).